PTTG1 (PTTG1 regulator of sister chromatid separation, securin)
Diseases named in the same sentence as PTTG1 in open-access papers (continued):
Sharing a sentence is not in itself a finding about the gene and the disease.
tumor (continued). "In this study we evaluated RNA and protein expression patterns of SP17, AKAP4 and PTTG1 in NSCLC cell lines and primary tumor samples from NSCLC patients, compared to normal lung cells and tissues." (PMID 25739119, 2015). "These investigators silenced PTTG1 expression in human A2780 OCA cells and investigated the effect on tumor formation in vitro and in vivo." (PMID 19014669, 2008). "The oncogenic potential of PTTG1 has been well characterized in mouse fibroblast (NIH3T3) cells, in which it induces proliferation and promotes tumor formation and angiogenesis." (PMID 17411443, 2007). "In this context a predictive marker like PTTG-1 might be valuable to come to a decision on the still controversially discussed question if a patient with stage I-IIIA NSCLC should be treated with adjuvant chemotherapy or radiation after a histologically confirmed R0-resection of the tumor." (PMID 16426442, 2006). "The oncogenic potential of PTTG1 has been well characterized in the mouse, particularly mouse fibroblast (NIH3T3) cells, in which it induces cell proliferation, promotes tumor formation and angiogenesis." (PMID 15649325, 2005). "Similarly, PTTG1 has been shown to influence NF-κB activation through its regulatory effects on FOXM1 expression, linking its activity to tumor progression and immune system modulation." (PMID 40072059, 2025). "Additionally, PTTG1 influences angiogenesis by regulating VEGF expression through HIF-1α and the PI3K/AKT/mTOR pathway, thereby enhancing CSC survival and tumor progression." (PMID 40072059, 2025). "Our immunohistochemistry results confirmed significantly higher expression of PTTG1 in tumor tissues compared to adjacent non-tumorous tissues, reinforcing their role as a major driver of HCC, as indicated by its large coefficient in the model." (PMID 40315269, 2025). "In addition, PTTG1 can inhibit the TGF-β1/SMAD3 signaling pathway, thereby suppressing apoptosis and promoting tumor cell growth." (PMID 41312363, 2025). "Furthermore, both RAC2 and PTTG1 promote the formation of a vascular niche by upregulating VEGF and contributing to angiogenesis, which further supports tumor growth and metastasis." (PMID 40072059, 2025). "This analysis revealed that seven cell populations exhibited a significant correlation with poorer patient outcomes, including tumor cell cluster 3 (highly expressing S100A2), cluster 8 (TK1), cluster 10 (PTTG1), cluster 12 (IGFBP5), cluster 13 (ISG15), cluster 16 (UPP1), cluster 17 (IL13RA2)." (PMID 38331898, 2024). "Simultaneous silencing of the PTTG1, PTTG2, and PTTG3P genes was performed in same MG-63 cells using siRNA to investigate their combined effects on key cellular processes such as cell cycle regulation, tumor growth, and other critical cellular functions." (PMID 39139816, 2024). "In addition, we explored the relationship between TRP-related prognostic features and TME and revealed strong correlations between ANLN, DLGAP5, FAM83A, PTTG1, and RHOV with tumor immune infiltration, immune checkpoints, and substance metabolism pathways." (PMID 39144144, 2024). "This might be since PTTG1 can influence CXADR at the precancerous stage, while it has a minimal impact on CXADR during the progression stage of the tumor." (PMID 37243239, 2023). "Notably, compared with PTTG1 and S100A8, approximately 50% MRS1-tumor cells expressed S100A7, with a 34-fold change than the expression percentage in MRS2-tumor cells." (PMID 37543645, 2023). "Additionally, these authors reported a positive correlation between PTTG1 protein concentration and serum alpha-fetoprotein (AFP), portal vein tumor thrombosis, tumor stage, and FGF levels." (PMID 35805898, 2022). "In the current review we focus on the pituitary tumor transforming gene (PTTG1)/delta like non-canonical notch ligand 1 (DLK1) axis as a potential therapeutic target to attenuate the progression of these pathological conditions." (PMID 35805898, 2022).
tumor (continued). "CDK1, HMMR, PTTG1, and TTK were positively correlated with tumor-infiltrate lymphocytes, which might involve tumor immune response." (PMID 34187556, 2021). "ACS and PTTG1 were downregulated in SREBP1-silenced and S1P-silenced tumor lysates." (PMID 34285190, 2021). "Significantly lower methylation levels of PTTG1 and TACC3 promoters were found in tumor tissues compared with normal tissues, which may account for the abnormal expression of the signature genes in LUAD." (PMID 34869385, 2021). "On the other hand, univariable analyzes of the separate series of tumor samples were statistically significant, which means that one tissue block per patient may be sufficient to assess CCNB1 and PTTG1 expression." (PMID 31801961, 2020). "Differently from PTTG1, the AKA role in tumor transformation is better known." (PMID 30911297, 2019). "Consistent with the elevated expression of Pttg1 in KaLwRij-derived plasma cells and the KaLwRij mouse tumour origin of the 5TGM1 cell line, 5TGM1 cells express high levels of Pttg1 (data not shown)." (PMID 26445238, 2015). "Pttg1 is overexpressed in a wide variety of endocrine and non-endocrine tumors, modulates tumor invasiveness and recurrence in several systems, and has functions in chromatid separation and cell cycle progression." (PMID 25906746, 2015). "Furthermore, the PMA-responsive region that we identified is located at nucleotides −406 to −246 upstream of the PTTG1 promoter and contains a binding site for KLF6, which is a zinc-finger transcription factor with tumor suppressor function." (PMID 23977008, 2013). "To test whether PTTG1-mediated senescence regulates tumor development and anti-neoplastic drug responses in vivo, we evaluated HCT116 WT and PTTG1−/− cells using subcutaneous xenografted tumors." (PMID 21858218, 2011). "In addition, PTTG1 and Fibroblast Growth Factor (FGF) together form a positive feedback loop and stimulate tumor angiogenesis." (PMID 18426563, 2008). "Experiments using tumor cell lines cultured in the presence or absence of 5-Aza reveal that hypomethylation seems not to be involved in PTTG1 over-expression." (PMID 18426563, 2008). "In this study, we have tested whether structural DNA alterations such as CpG methylation or LOH may explain PTTG1 expression levels in both cell lines and DTC tumor and healthy samples." (PMID 18426563, 2008). "Next to PTTG-1 status, other clinical parameters such as performance status (WHO 0/I vs. II/III; p= 0.0007), tumor stage (I/II vs. III/IV; p = 0.0117) and LDH level (serum levels ≤ 240 units/l vs. > 240 units/l; p = 0.0246) were also related to survival time using Kaplan-Meier analysis." (PMID 16426442, 2006). "Our data clearly demonstrate that over expression of PTTG1 in HEK293 results in an increase in cell proliferation induces cellular transformation in-vitro (increase in anchorage-independent growth) and promotes tumor formation in nude mice." (PMID 15649325, 2005). "Oncogenic function of PTTG1 was established by its overexpression in mouse fibroblast cell line (NIH 3T3) followed by assessment of its ability to induce cellular transformation and tumor formation in nude mice." (PMID 15649325, 2005). "To determine whether PTTG1 promotes tumor formation in nude mice, we subcutaneously injected nude mice with HEK293 cells expressing PTTG1 or mPTTG1." (PMID 15649325, 2005). "When overexpressed in PitNETs, PTTG1 accelerates cell cycle progression, promotes genetic instability, and activates the expression of growth factors such as fibroblast growth factor 2 (FGF-2) and vascular endothelial growth factor (VEGF), driving angiogenesis and enhancing tumor invasion." (PMID 41573212, 2025).
tumor (continued). "Therefore, the goals of this study were to evaluate the overall expression level of PTTG1 in BLCA tissues and to investigate its potential clinical value in BLCA patients, as well as the relationship between PTTG1 and tumor immune infiltration, and its transcriptional activity in BLCA tissues." (PMID 35768832, 2022). "Consequently, it might be another potential mechanism between PTTG1/HTLV-1 and tumor formation, such as ALT." (PMID 35281830, 2022). "Interestingly, PTTG1 is highly expressed in many different types of tumors, and enhances tumor cell growth and metastasis through complicated while not-fully-determined mechanisms." (PMID 30853662, 2019). "Furthermore, overexpression of a PTTG1 expression vector lacking the 3′UTR partially reverses the tumor suppressive effects of these miRNAs." (PMID 26320179, 2015). "Other genes in the area include PDGFRB, which plays an important role in tumor neovascularization, TGFBI, PTTG1, DOCK2 and DUSP1 (the latter three genes were speculated based on our internal studies), which were likely to be involved in ccRCC progression and development." (PMID 20671976, 2010). "To date, the evidence for the oncogenic function of PTTG1 has been obtained by overexpression of PTTG1 in mouse fibroblast cells (NIH3T3) followed by assessment of its ability to induce cellular transformation in vitro (colony formation in soft agar) and tumor formation in nude mice." (PMID 15649325, 2005). "Tumors having both positive and negative tumor areas for cytoplasmic BUB3 (30%), CCNB1 (28%), or PTTG1 (35%) were considered heterogeneous." (PMID 31801961, 2020). "+ or − indicates the tumor cells were positive or negative for the indicated CTA (SP17, AKAP4, or PTTG1), or for the CTA-specific IgG (n.a.= serum not available)." (PMID 25739119, 2015). "Perfect concordance was obtained between those genotypes obtained using tumor and healthy samples, giving additional support to Affymetrix results and supporting the theory that no LOH event had occurred involving PTTG1 gene." (PMID 18426563, 2008). "Our results were consistent with those of the meta-analysis such that GSN, SPTBN1, SFRP1 and MAF were down-regulated in most tumor samples with respect to their matched non-tumor samples whereas COX6C, RAD21, GSPT1, NME1 and PTTG1 were up-regulated." (PMID 19116033, 2008). "Although direct molecular interactions between RAC2 and PTTG1 have not been conclusively established, existing evidence indicates that these proteins co-regulate critical cancer-related pathways, including epithelial–mesenchymal transition (EMT), immune evasion, and tumor progression." (PMID 40072059, 2025). "When comparing patients group with strong PTTG-1 expression versus negative/low PTTG-1 expression statistically significant differences were noticed with respect to gender (p = 0.04), LDH level (p = 0.005), leucocyte count (p = 0.016) and tumor stage (p = 0.021)." (PMID 16426442, 2006).
cancer (128 papers, 2006 to 2025). A tumor composed of atypical neoplastic, often pleomorphic cells that invade other tissues. "PTTG1 has been implicated in cancer invasion and metastasis, with documented overexpression across various malignancies." (PMID 41264123, 2025). "Accumulating studies clarified that PTTG1 overexpression is associated with poor prognosis in various types of cancers." (PMID 38465336, 2024). "In conclusion, our findings shed light on novel cell types and genes associated with Wnt4Cre-labeled cells and highlight the critical role of Smarca4 in regulating tubular cell differentiation and the expression of the cancer-causing gene Pttg1 in the kidney." (PMID 37727504, 2023). "We have identified the crucial role of Smarca4 in regulating tubular cell differentiation and the expression of the cancer-causing gene Pttg1 in the kidney." (PMID 37727504, 2023). "High expression of PTTG1 was found to be associated with advanced cancers and short disease-free survival." (PMID 32824814, 2020). "Deregulation of genes involved in the mitotic checkpoint, such as BUB3, CCNB1, and PTTG1, can contribute to cancer development by increasing the risk of incorrect cell division, aneuploidy, and genomic instability." (PMID 31801961, 2020). "Since PTTG1 is highly expressed in a variety of cancers, understanding the mechanism underlying regulation of PTTG1 expression is essential for developing novel therapeutic strategies." (PMID 33250768, 2020). "Another study on the genetic changes of PTTG1 also excluded methylation and LOH as causes of PTTG1 aberration in human cancers." (PMID 27893422, 2017). "Transcriptional activators such as Sp1, nuclear factor-Y and β-catenin/T cell factor (TCF) have been implicated in the activation of human PTTG1 expression via the regulation of its promoter activity in various cancer cells." (PMID 23977008, 2013). "As PTTG1 (pituitary tumor transforming gene) abundance correlates with adverse outcomes in cancer treatment, we determined mechanisms underlying this observation by assessing the role of PTTG1 in regulating cell response to anti-neoplastic drugs." (PMID 21858218, 2011). "TNFα exposure to human-derived cancer cell lines caused PTTG1 induction." (PMID 35805898, 2022). "Specifically, PTTG1 is directly associated with cancer cell migration through MMP-2." (PMID 33498448, 2021). "PTTG1, associated with cancer invasiveness, can also be a diagnostic and prognostic marker for ACC." (PMID 34359790, 2021). "However, PTTG1 is highly abundant in several cancers and causes genome instability." (PMID 23878812, 2013). "Pituitary tumor-transforming gene 1 (PTTG1) is considered an oncogene, highly expressed in various cancers such as bladder cancer, ovarian cancer, and breast cancer." (PMID 41264123, 2025). "The findings establish PTTG1 as both a critical upstream regulator and downstream target within the NF-κB signaling network in cancer progression, highlighting its potential as a therapeutic target." (PMID 40072059, 2025). "While significant progress has been made in understanding the roles of RAC2 and PTTG1 in cancer biology, several knowledge gaps remain." (PMID 40072059, 2025). "This study conducted a preliminary exploration of PTTG1’s role in NB cells, revealing its high expression similar to that of an oncogene in most cancer cells, and correlating with NB cell proliferation, invasion, and migration." (PMID 41264123, 2025). "PTTG1 is a potential therapeutic target in various cancers, with research investigating its role as a biomarker and intervention target." (PMID 40072059, 2025). "The roles of RAC2 and PTTG1 in cancer biology underscore their potential as valuable prognostic markers and therapeutic targets." (PMID 40072059, 2025). "PTTG1 was initially identified in rat pituitary tumor cells and has been shown to functionally induce the transformation of mouse fibroblasts into malignant tumors." (PMID 39792809, 2025).
cancer (continued). "The findings revealed a notable up-regulation of PTTG1 in cancerous tissues and cell lines when compared to normal counterparts, aligning with observations from previous studies in various cancer types." (PMID 40877987, 2025). "What is more, the tamoxifen sensitivities of BCs were also connected to estrogen/PTTG1 influence, as tamoxifen resistance occurs more often in estrogen receptor-positive cancers." (PMID 40072059, 2025). "The upregulation of PTTG3P has been demonstrated to promote tumorigenesis by enhancing PTTG1 expression in cancer patients." (PMID 39139816, 2024). "Studies have reported that knockdown of pituitary tumor-transforming gene 1 (PTTG1) can downregulate c-myc-mediated aerobic glycolysis in cancer cells." (PMID 38465336, 2024). "Knockdown of PTTG1 strengthens the anti-cancer immune response in LUAD, implying PTTG1 is a potential target." (PMID 37583701, 2023). "Based on the promising potential of PTTG1 in cancer treatment, we explored the influence of PTTG1 on the treatment of PAAD in this study." (PMID 37243239, 2023). "Intriguingly, previous studies have shown that these molecules can contribute to the progression of a variety of cancers, with PTTG1 and CDCA3 being found to be prognostic biomarkers for KIRP." (PMID 37004005, 2023). "Cancer stemness is an important mechanism for mediating chemoresistance, and future studies should focus on establishing the role of PTTG1 in regulating stemness in PDAC." (PMID 37533202, 2023). "We obtained 74 dysregulated SRGs between normal and cancer tissues, among which six genes (RPS6KA6, ABI3, PTTG1, E2F1, CBX7, and SPOP) were associated with the OS of CC patients." (PMID 37768206, 2023). "ASPH, CDKN2A, E2F1, P3H1, and PTTG1 were identified as prognostic indicators of unfavorable outcomes within multiple cancer types." (PMID 37497116, 2023). "The high expression of CXADR and PTTG1 in cancer is significantly correlated with the short OS and DSS, further demonstrating the close relationship between the two factors." (PMID 37243239, 2023). "It has been demonstrated that PTTG1 sustains the migratory and invasive properties of cancer cells through the induction of the epithelial-to-mesenchymal transition (EMT)." (PMID 36230799, 2022). "The other eight types of cancers with upregulated PTTG1 include BLCA, CESC, CHOL, ESCA, GBM, KICH, PCPG, and READ." (PMID 36060253, 2022). "PTTG1 expression has been related to inflammation, angiogenesis, and fibrogenesis in cancer and experimental fibrosis." (PMID 35805898, 2022). "The data of RNA sequence and immunohistochemical staining was used to analyze the potential role of PTTG1 in human pan-cancer but the analysis of multi-omics is absence." (PMID 35281830, 2022). "Intriguingly, it was found that the expression levels of both PRR11 and PTTG1 were extremely correlated to genes involved in the cell cycle across various cancer types." (PMID 36060253, 2022). "PTTG1 sustains the migratory and invasive properties of cancer cells through the induction of the epithelial-to-mesenchymal transition (EMT)." (PMID 36230799, 2022). "Current evidence demonstrated that cancer testis antigens (CTA) such as pituitary tumor transforming gene 1 (PTTG1), A-kinase anchor protein 4 (AKAP4), and sperm protein 17 (SP17) are potential immunotherapeutic targets in NSCLC." (PMID 35463817, 2022). "On the other hand, pituitary tumor-transforming gene 1 (PTTG1) is a regulator of chromosome stability and is shown to aggravate cancer progression." (PMID 34025420, 2021). "PTTG1, an oncogene, has the ability to regulate the self-renewal and epithelial mesenchymal transformation of cancer stem cells." (PMID 34530829, 2021). "The five prognostic DCLs tended to condense around the well-known cancer gene ESPL1, and the transcriptional synchrony between ESPL1 and PTTG1 (another well-known cancer gene) tended to be elevated in patients of adverse prognosis." (PMID 34856998, 2021).